PHLPP2 (PH domain and leucine rich repeat protein phosphatase 2)
Diseases named in the same sentence as PHLPP2 in open-access papers (continued):
Sharing a sentence is not in itself a finding about the gene and the disease.
cancer (continued). "Interestingly, recent studies have identified PHLPP2 as a bona fide target for a number of oncogenicmicroRNAs (miRNAs), including miR-372, miR-224 and miR-17~92, in difference cancer types." (PMID 26760962, 2016). "We checked whether PHLPP2 dephosphorylates AMPKα in other cancer cells." (PMID 34608126, 2021). "Interestingly, PHLPP2, which is target of hsa-miR-15a-5p and hsa-miR-26b-5p, is involved in the control of autophagy in cancer, suggesting that this gene may also be related to autophagic dysfunction in the brain." (PMID 32872134, 2020). "To investigate the expression of PHLPP2 in HCC cell lines, we analyzed the Cancer Cell Line Encyclopedia (CCLE)-Liver database, as well as conducted RT-qPCR and Western blot analyses." (PMID 38199981, 2024). "Given that miR‐25‐3p has a role in inhibiting PHLPP2 and activating AKT signaling in cancer progression, the study suggests a role of the METTL3‐miR‐25‐3p‐PHLPP2‐AKT axis in promoting cigarette smoking‐induced PDAC tumorigenesis." (PMID 35560957, 2023). "Due to the potential clinical significance of PHLPP2 in CRC, its role cancer biology aroused our attention." (PMID 35281874, 2022). "We show that PHLPP2 has a divergent catalytic site, exhibits no activity in vitro, and that cancer genomics does not support a role for either PHLPP1 or PHLPP2 in cancer." (PMID 40168118, 2025). "Although genetic ablation of either or both genes in mice is not lethal and results in no reported predisposition to cancer, an evolutionary pressure of some sort has retained both PHLPP1 and PHLPP2 in vertebrates." (PMID 40168118, 2025). "Collectively, our findings reveal that TRIM22 regulates cancer cell senescence by modulating the proteasomal degradation of PHLPP2 in HCC cells, suggesting that TRIM22 could potentially serve as a therapeutic target for treating cancer." (PMID 38199981, 2024). "In recent years, many studies have shown that PHLPP2 is generally not expressed in a wide-ranging of cancer biological processes such as cancer cell proliferation, cancer metastasis and tumorigenesis." (PMID 37576883, 2023). "Recently, many studies have shown that the expression of PHLPP2 is universally absent in a variety of cancers and plays a key role in a wide range of biological processes, including cancer cell proliferation, metastasis, autophagy and apoptosis." (PMID 36101384, 2022). "According to that both PHLPP1 and PHLPP2 expressions are lost in diverse cancers, but their role in progression of cancers has not been identified." (PMID 31863623, 2020). "The inverse correlation between BMI‐1 and PHLPP1/PHLPP2 expression was observed in PTEN positive but not PTEN negative cancers." (PMID 31863623, 2020). "In summary, our results for the first time showed that down‐regulation of BMI‐1 in cancer cells might affect expression of PHLPP1 and PHLPP2." (PMID 31863623, 2020). "However, the same miRNA can be oncogenic by targeting PH domain leucine-rich-repeat protein phosphatases 1 and 2 (PHLPP1 and PHLPP2) in NSCLC, thereby inducing proliferation of the cancer cells." (PMID 30944831, 2019). "Those pathways specifically altered in primary tumors were associated with an abnormally increased expression of genes that are involved in focal adhesion (e.g., PRKCA, CRK, and BCL2), PI3K-Akt signaling (e.g., PHLPP2, PRKCA, PPP2R3A and KIT) and cancer pathways (e.g., COL4A5, LAMC1 and BCL2L1)." (PMID 27662660, 2016).
cancer (continued). "The results revealed that the expression of either PHLPP1 or PHLPP2 was significantly decreased in carcinomas relative to adjacent noncancerous epithelial tissues." (PMID 25793736, 2015). "The expression levels of PHLPP1 and PHLPP2 were found to be lost or decreased in carcinomas compared with the adjacent noncancerous mucosae, which was certificated by qRT-PCR and immunohistochemical staining." (PMID 25793736, 2015). "Furthermore, we show that cancer genomics does not support a role for either PHLPP1 or PHLPP2 in cancer." (PMID 40168118, 2025). "Taken together with the observation that PHLPP2 is a pseudophosphatase, the proposed role of PHLPP in cancer deserves further scrutiny, with an emphasis on its noncatalytic functions." (PMID 40168118, 2025).
skeletal system disorder (1 paper, 2018). A disease involving the skeletal system. "Little is known, however, regarding the relationship between PHLPP2 and the skeletal system disorders." (PMID 29887852, 2018).
PHLPP2 also shares sentences with these, for which no sentence is quoted: adenocarcinoma (2 papers); colon adenocarcinoma (2); metabolic disease (2); acute lung injury (1); acute lymphocytic leukemia (1); atrial fibrillation (1); B cell lymphoma (1); breast invasive carcinoma (1); cardiovascular diseases (1); chronic myeloid leukemia (1); chronic obstructive pulmonary disease (1); clear cell renal cell carcinoma (1); colorectal (1); cone-rod dystrophy (1); delirium (1); dementia (1); diabetes (1); ependymoma (1); gallbladder cancer (1); gastric tumor (1); Hyperinsulinemia (1); infection (1); liver cancer (1); lymphoma (1); metastatic melanoma (1); metastatic prostate carcinoma (1); myeloma (1); myocardial infarction (1); non-alcoholic fatty liver disease (1); Optic neuropathy (1).
A further 6 diseases each share a sentence with PHLPP2 in 1 paper.